CISD2 (CDGSH iron sulfur domain 2)
Diseases named in the same sentence as CISD2 in open-access papers (continued):
Sharing a sentence is not in itself a finding about the gene and the disease.
lymphoma (1 paper, 2023). A malignant (clonal) proliferation of B- lymphocytes or T- lymphocytes which involves the lymph nodes, bone marrow and/or extranodal sites. "On the other hand, using HPA dataset, the protein expression of CISD2 in lymphoma tissues were higher than lymph node tissues." (PMID 38155967, 2023).
Marfan syndrome (1 paper, 2024). A disorder of the connective tissue. "Cisd2, a master gene for Marfan syndrome, plays an essential role in maintaining mitochondrial integrity and functions." (PMID 39226169, 2024).
metabolic syndrome (1 paper, 2019). A cluster of metabolic risk factors for CARDIOVASCULAR DISEASES and TYPE 2 DIABETES MELLITUS. "Thus, it is highly possible that the onset of some adult diseases like metabolic syndrome may be caused by an alteration in Cisd2 expression." (PMID 31798625, 2019).
nonalcoholic steatohepatitis (1 paper, 2022). "Hepatocyte-specific Cisd2-haploinsufficiency (Cisd2hKO+/−) aggravates nonalcoholic steatohepatitis (NASH) development and upregulates expression of the mRNAs responsible for cholesterol synthesis, fibrosis and lipid metabolism." (PMID 35247253, 2022).
oligodendroglioma (1 paper, 2022). A well-differentiated (WHO grade II), diffusely infiltrating neuroglial tumor, typically located in the cerebral hemispheres. "Specifically, we found that CISD2 expression was not only lower in oligodendroglioma than in GBM but was also lower in the 1p/19q codeleted tumors compared to the 1p/19q noncodeleted tumors." (PMID 35493303, 2022).
renal fibrosis (1 paper, 2021). A final common manifestation of a wide variety of chronic kidney diseases characterized by glomerulosclerosis and tubulointerstitial fibrosis. "(A) Decreased expression of HIST1H1B, a histone protein (B) increased expression of ACTA2, a marker of renal fibrosis, (C) decreased expression of NCLN, a part of the endoplasmic reticulum, and (D) decreased expression of CISD2, which is involved in mitochondrial autophagy." (PMID 33687326, 2021).
trauma (1 paper, 2022). "Consistent with the findings of previous animal and cellular studies, the plasma levels of CISD2 in patients with SCI (n = 2) and head trauma (n = 11) were non-significantly decreased compared with those in healthy controls." (PMID 35453528, 2022).
cancer (24 papers, 2016 to 2025). A tumor composed of atypical neoplastic, often pleomorphic cells that invade other tissues. "Previous studies have revealed that CISD2 deficiency impairs cell proliferation in corneal epithelial cells and in cancer cell lines." (PMID 38263133, 2024). "The upregulation of either CISD1 or CISD2 reduces the susceptibility of human cancers to ferroptosis inducers by limiting mitochondrial iron uptake." (PMID 37345031, 2023). "It highlights the urgent need to explore the potential therapeutic strategy for cancer and age-associated diseases based on CISD2 manner." (PMID 38155967, 2023). "CISD2 is an evolutionarily highly conserved protein that performs an integral function in aging-related diseases and cancers, including neuronal loss, cell drug resistance, cell proliferation, migration and invasion." (PMID 35436415, 2022). "In this study, based on the analysis of public database, we found that CISD2 has an aberrant expression in most types of human cancers and is associated with poorer overall survival (OS) for NSCLC." (PMID 33598426, 2020). "These consistent findings consolidate the notion that CISD2 expression in cancer cells is associated with changes in mitochondrial function and cellular oxidative stress." (PMID 28928421, 2017). "Currently, the role of CISD2 in cancers causes more interest." (PMID 38155967, 2023). "We investigated whether CISD2 is associated with the molecular biological characteristics of cancer." (PMID 33598426, 2020). "Our finding that CISD2 expression levels is associated with patient survival implies that CISD2 could be involved in behavioral changes of cancer cells linked with cancer progression." (PMID 28928421, 2017). "Future studies are required to increase our understanding the impact of CISD2 on signaling pathways in cancer cells." (PMID 38263133, 2024). "CISD2 is a versatile protein that has notable implications in both age-related diseases and cancers." (PMID 38263133, 2024). "Conversely, downregulation or knockdown of CISD2 expression has been shown to inhibit tumor growth and improve the efficacy of cancer treatments." (PMID 39605902, 2024). "In tumorigenesis, CISD2 can regulate cancer cell growth, proliferation, invasion, biosynthesis, and progression through various cellular processes, including mitochondrial iron metabolism, redox regulation, lipid metabolism, and cellular stress response." (PMID 38155967, 2023). "Several studies suggest a close correlation between CISD2 expression and resistance to ferroptosis in human cancers." (PMID 37345031, 2023). "Cancer cells preferentially produce a protein called CISD2 (nutrient deprivation autophagy factor-1; NAF-1), a homodimer protein composed of metal and sulfur." (PMID 37345031, 2023). "A study in cancer cell lines has shown that the anti-autophagic role of BCL2 requires direct interaction with CISD2." (PMID 36774344, 2023). "In contrast, the genetic knockdown of CISD2 or the administration of pioglitazone increases mitochondrial ferrous iron and lipid peroxidation, leading to the vulnerability of cancer cells to ferroptosis induction by sulfasalazine." (PMID 37345031, 2023). "CDGSH iron sulfur domain 2 (CISD2) is an evolutionarily conserved protein that is involved in several cancers." (PMID 35493303, 2022). "Collectively, we determined that CISD2 plays a role in the molecular biological characteristics of cancer." (PMID 33598426, 2020). "We additionally employed the prognostic value of CISD2 in cancers within the RNA sequencing data in TCGA to assess how CISD2 expression relates to prognosis in a range of cancer types." (PMID 33598426, 2020). "Bioinformatics of pan-cancer analysis from The Cancer Genome Atlas show that CISD2 has an aberrant expression in most types of human cancers." (PMID 33598426, 2020).
cancer (continued). "We then utilized in vitro cancer cell line model, in which the expression level of CISD2 was interfered by using siRNA or shRNA techniques, to observe their effects on cancer associated phenotypes." (PMID 28928421, 2017). "At present, studies on CISD2 mainly focus on age-related diseases and cancer." (PMID 39596826, 2024). "CISD2 is principally localized in the mitochondrial outer membrane and has a vital function in the aging process related to mitochondrial dysfunction, human neurodegenerative diseases, and various human cancers." (PMID 35493303, 2022). "On the other hand, in HCC cancer cells, CISD2 may also benefit tumor cells by supporting energetic and metabolic demands via mediating mitochondrial functions." (PMID 33916843, 2021). "CISD2 has an aberrant expression in several types of human cancers." (PMID 33598426, 2020). "CISD2 plays an important role in Fe-S cluster transfer and promotes cancer proliferation." (PMID 33598426, 2020). "CISD2 could represent a key regulatory link between iron metabolism and cellular ROS in cancer cells due to its unique 2Fe-2S cluster coordinated by 3Cys:1His, which is labile and redox-active." (PMID 33598426, 2020). "CISD2 was known to have aberrant expression in several types of human cancers." (PMID 28928421, 2017). "In the present study, we aimed to understand whether CISD2 expression is associated with the formation of lung ADC, and with the prognosis for patients with this cancer type." (PMID 28928421, 2017). "In such a scenario, the expression level of CISD2 could be a marker reflecting the levels of accumulated oxidative stress in cancer cells." (PMID 28928421, 2017). "Given that CISD2 expression might affect cancer cell proliferation, we tested whether it would influence tumor growth phenotypes in vivo." (PMID 28928421, 2017). "The potential link between high CISD2 expression and poorer PFS in LSCC might rely on the regulation of mitochondrial performance by CISD2 in cancer cells." (PMID 27007153, 2016). "Furthermore, CISD2 also participate in the regulation of cellular iron and active oxygen species (ROS) homeostasis and hence is critical in the process of cancer cell proliferation and tumor progression." (PMID 27007153, 2016). "CDGSH iron sulfur domain 2 (CISD2) is localized in the outer mitochondrial membrane and mediates mitochondrial integrity and lifespan in mammals, but its role in cancer is unknown." (PMID 26565812, 2016). "Intriguingly, in contrast to the tumor-suppressive role of Cisd2 at an early stage during spontaneous development of HCC in a mouse model, it seems that human CISD2 protein is associated with oncogenic properties after malignant transformation in various cancer cell types, including HCC." (PMID 33916843, 2021). "In addition, the selective regulation of AKT/mTOR signaling, such as screening for CISD2 expression, might prove valid for cancer treatment when combined with 5‐FU." (PMID 28857517, 2017). "Therefore, a reasonable scenario emerges: during the process of cancer formation or progression, the upregulation of CISD2 offers cancer cells critical survival and proliferation signals by providing them with greater antioxidant capacity to counteract gradually elevated ROS levels." (PMID 28928421, 2017). "In addition to establishing an association of important clinical relevance, we also provide some possible molecular explanations of how the upregulation of CISD2 expression could foster cancer cell formation and progression." (PMID 28928421, 2017). "These research findings demonstrate that CISD1, CISD2, and CISD3 have the potential to modulate ferroptotic cell death in cancer cells through the regulation of their ISCs." (PMID 37345031, 2023). "Additionally, CISD2 was found to positively correlate with activated memory T cells and negatively correlate with regulatory T cells (Tregs) and plasma cells in COAD, as well as being significantly associated with several immune-related and cancer-related pathways." (PMID 37304867, 2023).
cancer (continued). "Cancer cells produce CISD2 (nutrient deprivation autophagy factor-1; NAF-1), a metal-sulfur [2Fe-2S] homodimer protein that acts as a prognostic marker in a variety of cancers." (PMID 36338346, 2022). "CISD2, which was found to be significantly upregulated in lung ADC samples, stimulates cancer cell proliferation and survival through elevated reactive oxygen species levels and ultimately leads to poor prognosis." (PMID 34616431, 2021). "As CISD2 is a conservative protein, bioinformatics of pan-cancer analysis from TCGA show that the expression of CISD2 is generally increased in 27 types of human cancers, except for LAML, KIRP, and READ, indicating that CISD2 could play a critical role in tumorigenesis." (PMID 33598426, 2020). "Several studies reveal that various types of cancers are accompanied by overexpression of NEET proteins and the CISD2 expression level has been proposed as an independent prognostic marker for survival in cancer patients including pancreatic and gastric cancers." (PMID 33916457, 2021). "The results showed that the expression of CISD2 was significantly higher in individual cancer stages compared with adjacent normal tissues, but not linearly related to pathological stages of LUAD or LUSC." (PMID 33598426, 2020). "In this context, targeted inhibition of CISD2 specifically in the cancer cells rather than CISD2 activation may be more appreciated to benefit the HCC patients." (PMID 33916843, 2021).
tumor (20 papers, 2016 to 2025). "And potential confounding variables, such as patient age, gender, and tumor stage, may have influenced the observed associations between CISD2 expression and clinical outcomes." (PMID 37304867, 2023). "In vivo experiments further demonstrated that targeting the Smad3/CISD2 axis significantly suppressed xenograft tumor growth and activated ferroptosis." (PMID 41413023, 2025). "Advanced stages (III–IV) were linked to CISD2, ATG5, and DDIT4, while elevated levels of MAP1LC3A, PRDX6, CISD2, and ATG2 were tied with higher tumor grades." (PMID 39857718, 2025). "Conversely, overexpression of CISD2 can reduce the accumulation of iron and ROS in tumor cells, enhance the antioxidant system, resist oxidative stress, and promote tumor cell growth." (PMID 39605902, 2024). "Pioglitazone, a known CISD2 inhibitor, also can induce excessive accumulation of iron and ROS, overcoming ferroptosis resistance in tumor cells." (PMID 39605902, 2024). "Cul5, Ube2f and Rnf19b were top three hits in both tumor and spleen, while Zgpat, Athl1 and Cisd2 were top three hits in TDLN." (PMID 38242867, 2024). "On the other hand, in other scenarios CISD2 can promote tumor cell growth and survival, potentially making it a target for the development of anticancer therapies." (PMID 38263133, 2024). "Recently, numerous studies have demonstrated that CISD2 is upregulated in various tumors, where it promotes tumor cell proliferation by regulating calcium metabolism, oxidative stress, mitochondrial quality control, autophagy, and ferroptosis." (PMID 39605902, 2024). "Upregulation of CISD2 has often been correlated with aggressive tumor characteristics such as increased tumor size and advanced clinical stage." (PMID 38155967, 2023). "Patients with elevated CISD2 expression exhibited increased infiltration of tumor-eradicating CD8-positive T cells, leading to a more favorable prognosis." (PMID 37304867, 2023). "According to the adjustments for tumor purity, CISD2 expression demonstrated a significant correlation with most of the gene markers of functional T cells (CD8+ T, Th1, Th2, Treg, and exhausted T cells), B cells, and neutrophils in LGG." (PMID 35493303, 2022). "As tumor cells exhibit the ability to grow indefinitely and can survive for a long time, the role of CISD2 in tumors has attracted much interest." (PMID 35493303, 2022). "But the statistical results showed that CISD2 expression was significantly correlated with several types of tumor-infiltrating immune cells in LGG, including B cells, CD8+ T cells, neutrophils, and CD4+ T cells in TIMER." (PMID 35493303, 2022). "According to the adjustments for tumor purity, CISD2 expression demonstrated a significant correlation with 8 out of 51 immune cell markers in GBM and 30 out of 51 immune cell markers in LGG." (PMID 35493303, 2022). "Accordingly, the paradoxical role of CISD2, namely oncogenic or tumor-suppressive, is dependent on the stage during tumor development." (PMID 33916843, 2021). "By comparing the HCC RNA-seq data of 371 tumor tissues with that of 50 adjacent normal tissues from TCGA, we found that CISD2 was upregulated in HCC." (PMID 34485112, 2021). "We further examined the levels of mitochondrial ROS to evaluate the involvement of mitochondria in the tumor inhibitory effects of CISD2 knockdown A549 cells." (PMID 33598426, 2020). "CDGSH iron sulfur domain 2 (CISD2) is a survival gene and plays an important role in the redox reaction, longevity, tumorigenesis, and tumor progression." (PMID 33344463, 2020). "Due to large variation no statistical significance was established in our study, additional in vivo studies will be needed in order to establish the role of CISD2 in tumor development in vivo." (PMID 28928421, 2017). "Since tumor cells have the capacity for unlimited growth and show a long lifespan, researchers have gradually focused on the role of CISD2 in tumors." (PMID 28857517, 2017).
tumor (continued). "In this manuscript, we aimed to reveal the role of CISD2 in tumor development, metastasis and modulation of the sensitivity of GC cells to 5‐FU." (PMID 28857517, 2017). "Consistent with the mRNA analysis, CISD2 protein was also over-expressed in LSCC tissues compared to the surrounding non-tumor regions." (PMID 27007153, 2016). "Univariate analysis showed that pathological differentiation (P = 0.023), tumor site (P = 0.047), T stage (P < 0.001), N stage (P < 0.001) and CISD2 expression (P < 0.001) were significant prognostic factors for PFS in LSCC." (PMID 27007153, 2016). "CISD2 was mainly localized to the tumor cell cytoplasmic with strong nuclei staining while little or no expression of CISD2 was observed in the normal epithelial cells." (PMID 27007153, 2016). "As tumor cells have a long lifespan due to the unlimited growth capacity, all of these observations combined suggest that CISD2 plays an important role in tumor cells." (PMID 26565812, 2016). "Previous studies suggest that CISD2 may play a role in promoting tumor cell proliferation and drug resistance through ferroptosis and ferritinophagy." (PMID 39605902, 2024). "Consequently, CISD2 plays a crucial role in controlling the tumor microenvironment by regulating tumor homeostasis." (PMID 37304867, 2023). "Overexpression of CISD2 in HCC is responsible for sorafenib resistance in tumor cells." (PMID 36759819, 2023). "Collectively, these bioinformatics data suggest that CISD2 could modulate macrophage polarization from M1 to M2 with tumor progression, providing a direction for further research." (PMID 35493303, 2022). "We propose a model of CISD2–ROS–EGR1/GPX3 axis signaling, in which increased levels of CISD2 contribute to the neutralization of excessive ROS production, which would otherwise increase antitumor activity mediated at least by the tumor suppressors EGR1 and GPX3." (PMID 28928421, 2017). "CISD2 expression was observed in the tumor cells in 188/210 (89.5%) of the samples." (PMID 26565812, 2016). "CISD2-silenced cells had a significantly decreased ability to form tumors in nude mice compared to vector-transfected cells, as indicated by the final xenograft tumor weight, volume and the tumor growth curves." (PMID 26565812, 2016). "Consequently, CISD2 is hypothesized to impede tumor growth by promoting immune cell infiltration and preserving endoplasmic reticulum calcium homeostasis." (PMID 37304867, 2023). "In accordance with the correlation analysis of CISD2 and immune cells, CISD2 exhibits a positive association with common lymphoid progenitors, granulocyte-monocyte progenitors, neutrophils, and CD8-positive T cells, providing an extensive insight into its influence on the tumor immune landscape." (PMID 37304867, 2023). "By modulating the cell cycle and mediating immune infiltration, CISD2 may inhibit COAD development by influencing tumor immune microenvironment equilibrium, providing valuable insights into the relevance and potential impact of the research results on the COAD research field." (PMID 37304867, 2023). "A negative association between CISD2 and epithelial-mesenchymal transition, as well as apical junctions, may impede tumor proliferation and metastasis." (PMID 37304867, 2023). "In addition, patients with high CISD2 expression have been linked to a higher HR and significantly poorer OS in LUAD, UVM, HNSC, LGG, KICH, and LIHC, suggesting that high CISD2 expression could act as an indicator of tumor prognosis." (PMID 33598426, 2020). "The mRNA expression level of CISD2 (P = 2.07 × 10−12) and NIT2 (P = 1.23 × 10−7) were both significantly higher in the LUAD tumor tissues (n = 57) from TCGA database." (PMID 39003419, 2024). "The result showed that the mRNA expression level of CISD2 and NIT2 were also higher in LUAD tumor tissues (n = 49) compared with paired adjacent non-tumor tissues (P = 4.31 × 10−3, P = 7.38 × 10−6)." (PMID 39003419, 2024).